ELFN2 (extracellular leucine rich repeat and fibronectin type III domain containing 2)
Description:
Inhibits phosphatase activity of protein phosphatase 1 (PP1) complexes.
Synonyms: KIAA1904; LRRC62; PPP1R29; dJ63G5.3
Tractability: Antibody: UniProt predicts a signal peptide or a membrane-spanning region; its Gene Ontology location is reachable by antibodies, with medium confidence. PROTAC: ubiquitination databases record sites on it; its protein half-life has been measured.
Gene: Protein-coding gene on chromosome 22 (37,367,960 to 37,427,479, reverse strand). Ensembl gene ENSG00000166897.
Subcellular location: Membrane
Subcellular location (Human Protein Atlas): Nucleoplasm; Vesicles
Gene Ontology:
Molecular function: signaling receptor activity
Biological process: chemical synaptic transmission; establishment of protein localization; synaptic membrane adhesion
Cellular component: extracellular region; plasma membrane; membrane; postsynaptic density membrane; synapse
Genetic constraint (gnomAD): Loss-of-function variants: 17 observed, 45.03 expected, observed/expected ratio (o/e) 0.38, 90% interval 0.26 to 0.57. The upper end of that interval is the gene's LOEUF score, 0.57, which puts it in group 2 of 6, group 1 being the genes least tolerant of losing a copy. Missense variants: 922 observed, 1,207.7 expected, observed/expected ratio (o/e) 0.76, 90% interval 0.72 to 0.81. Synonymous variants: 550 observed, 556.57 expected, observed/expected ratio (o/e) 0.99, 90% interval 0.92 to 1.06.
Homologues: Orthologues: chimpanzee ELFN2 (100% identical), macaque ELFN2 (99% identical), dog ELFN2 (97% identical), pig ELFN2 (97% identical), mouse Elfn2 (96% identical), rat Elfn2 (96% identical), rabbit ELFN2 (95% identical), tropical clawed frog elfn2 (70% identical), zebrafish ELFN2 (58% identical), zebrafish elfn2a (30% identical), Drosophila melanogaster kek3 (14% identical), Caenorhabditis elegans sma-10 (11% identical), and 2 more. Paralogues in human: ELFN1 (48% identical), LRIG1 (15% identical), LRIG2 (15% identical), LRIG3 (15% identical), LGR6 (12% identical), LRIT1 (11% identical), LRIT3 (11% identical), LGR5 (11% identical), TRIL (11% identical), LGI1 (10% identical), LGR4 (10% identical), LGI2 (10% identical), and 10 more.
Diseases named in the same sentence as ELFN2 in open-access papers:
ELFN2 is named in the same sentence as 15 diseases in open-access papers, as found by Europe PMC text mining. Sharing a sentence is not in itself a finding about the gene and the disease. The quoted sentences say what the papers report.
glioblastoma (3 papers, 2021 to 2024). The most malignant astrocytic tumor (WHO grade IV). "ELFN2 is also involved in glioblastoma cell autophagy, pancreatic cancer radiotherapy resistance, gastric cancer invasion, and endometrial cancer progression." (PMID 38902737, 2024). "LINC00470 could enhance the expression of ELFN2 and play a dominant role in the regulation of GBM cell autophagy to promote the development of glioblastoma." (PMID 34249684, 2021). "In glioblastoma, LINC00470 could enhance the expression of ELFN2 through adsorption of miR-101, and also affect the methylation level of ELFN2 by decreasing H3K27me3 occupancy." (PMID 36533073, 2022).
astrocytoma (2 papers, 2024 to 2025). "Extracellular leucine‐rich repeat and fibronectin type III domain containing 2 (ELFN2) is highly expressed in astrocytoma patients and significantly correlated with overall survival." (PMID 39233332, 2024).
gastric cancer (2 papers, 2022 to 2024). A primary or metastatic malignant neoplasm involving the stomach. "ELFN2 is a vital postsynaptic adhesion molecule in brain behaviour and ELFN2 signalling pathway also acts as the downstream molecule of CST4, which promoted aggressiveness in gastric cancer." (PMID 35685372, 2022).
glioma (2 papers, 2021). A benign or malignant brain and spinal cord tumor that arises from glial cells (astrocytes, oligodendrocytes, ependymal cells). "As a dominant regulator of glioma cell autophagy, LINC00470 promoted the expression of ELFN2 through sponge of exosomal miR-101 to distract glioma cell autophagy." (PMID 34540663, 2021). "As a dominant regulator of glioma cell autophagy, LINC00470 promoted the expression of ELFN2 through sponge of miR-101 to distract glioma cell autophagy." (PMID 33663509, 2021).
Anxiety (1 paper, 2022). Intense feelings of nervousness, tension, or panic often arise in response to interpersonal stresses. "As ELFN2 mainly inhibits glutamate release, Elfn2 knockout mice display multiple neuropsychiatric phenotypes, including increased seizure susceptibility, hyperactivity, and anxiety/compulsivity." (PMID 35250486, 2022).
lung carcinoma (1 paper, 2021). "The other upregulated genes ELFN2, QSOX1, and MUC1 have been shown to directly promote metastasis in various cancers, including lung cancer." (PMID 34172784, 2021).
viral infection (1 paper, 2025). "It is worth noting that genes relating to innate immune response to viral infection (e.g., DHX58, MX1, IFITM-like), cell structure integrity (e.g., ANGPTL3, ANGPTL4, ELFN2, COL5A3) and transcription factors (e.g., TUB) remained upregulated throughout the acute phase of infection (1–6 dpi)." (PMID 40758745, 2025).
cancer (2 papers, 2024 to 2025). A tumor composed of atypical neoplastic, often pleomorphic cells that invade other tissues. "The HLM score was constructed based on six genes, AGXT, TRIB2, ELFN2, PCDHB10, CALCA, and CD79A, which have been previously reported to be associated with the tumorigenesis and progression of various cancer types, including CRC, as well as chemotherapy resistance." (PMID 38902737, 2024). "In our eight signature genes (ARL6IP4, ATP2A1, CRYAB, ELFN2, MAP2, MAT1A, ORC1, and POU4F1), prior research has elucidated the expression and function of several genes involved in the initiation and progression of cancer." (PMID 41567198, 2025).
tumor (2 papers, 2020 to 2021). "Most ES expressed neurexin-1 (96%) and ELFN2 (96%), whereas SLC38A11 and CCDC190 were detected in just 41% and 67% of the tumours examined, respectively." (PMID 34403115, 2021).
ELFN2 also shares sentences with these, for which no sentence is quoted: endometrial cancer (1 paper); infection (1); neurological diseases (1); pancreatic cancer (1); Parkinson’s (1); Stroke (1).